CLMB (calcimembrin)
Synonyms: C16orf74; MGC17624; MICT1; ASRA
Tractability: Antibody: the Human Protein Atlas places it where antibodies can reach.
Gene: Protein-coding gene on chromosome 16 (85,690,084 to 85,751,129, reverse strand). Ensembl gene ENSG00000154102.
Subcellular location (Human Protein Atlas): Plasma membrane; Centrosome
Gene Ontology:
Molecular function: protein binding
Biological process: adaptive thermogenesis
Cellular component: membrane; plasma membrane
Genetic constraint (gnomAD): Loss-of-function variants: 11 observed, 5.17 expected, observed/expected ratio (o/e) 2.13. That is too few expected variants to judge how well the gene tolerates losing a copy. Missense variants: 141 observed, 77.47 expected, observed/expected ratio (o/e) 1.82, 90% interval 1.58 to 1.97. Synonymous variants: 60 observed, 33.39 expected, observed/expected ratio (o/e) 1.8, 90% interval 1.43 to 1.97.
Homologues: Orthologues: chimpanzee C16H16orf74 (99% identical), macaque C20H16orf74 (93% identical), pig C16orf74 (78% identical), mouse 1190005I06Rik (74% identical), rat C19h16orf74 (74% identical), dog C16orf74 (63% identical), guinea pig C16orf74 (63% identical).
Diseases named in the same sentence as CLMB in open-access papers:
CLMB is named in the same sentence as 21 diseases in open-access papers, as found by Europe PMC text mining. Sharing a sentence is not in itself a finding about the gene and the disease.
CLMB shares sentences with these, for which no sentence is quoted: cancer (9 papers); bladder cancer (5); pancreatic cancer (4); tumor (4); cervical cancer (3); Insulin resistance (2); Obesity (2); pancreatic ductal adenocarcinoma (2); adrenocortical carcinoma (1); cervical tumour (1); colon adenocarcinoma (1); glioblastoma (1); head and neck cancer (1); head and neck squamous cell carcinoma (1); lung adenocarcinoma (1); lymph node metastasis (1); metabolic disease (1); pancreatic adenocarcinoma (1); prostate carcinoma (1); tongue cancer (1); type 2 diabetes (1).